XRCC2 (X-ray repair cross complementing 2)
Diseases named in the same sentence as XRCC2 in open-access papers (continued):
Sharing a sentence is not in itself a finding about the gene and the disease.
cancer (continued). "Further study demonstrated that XRCC2 promoter is hyperactivated in cancer cell lines, and diphtheria toxin A (DTA) gene driven by XRCC2 promoter specifically eliminates cancer cells." (PMID 29549248, 2018). "Here we identified the ~2.1 kb promoter of XRCC2, similar to ~6.5 kb RAD51 promoter, as also hyperactivated in cancer cells." (PMID 29549248, 2018). "XRCC2 and XRCC4 showed higher expression in tumor tissues and cells with respect to non cancer tissues/cells." (PMID 24616890, 2014). "Moreover, single-cell RNA sequencing analysis revealed that CCNB2, XRCC2, and CENPI are enriched in cancer cells within BC tissues." (PMID 40202151, 2025). "The immunohistochemistry results revealed significantly higher XRCC2 expression levels in cancer tissues compared to adjacent normal tissues, corroborating its role as a tumor-associated biomarker in LUAD." (PMID 39090304, 2024). "How to reconcile the controversy that the change of XRCC2 mRNA between paratumors and tumors, or between normal and cancer cells, is not as dramatic as the change of XRCC2 promoter activity assayed by exogenous reporter genes?" (PMID 29549248, 2018). "Currently, it is not clear how to use low cancer risk genes in management and risk counseling (NBN, XRCC2, GALNT12, etc.), since recommendations should be based either way on the personal and family history of cancer." (PMID 26484312, 2015). "XRCC2 and XRCC3 proteins are structurally and functionally related to RAD51, which plays an important role in the homologous recombination, the process being frequently involved in cancer transformation." (PMID 24728564, 2015). "The most frequently amplified genes across the pan-cancer atlas were BRIP1 (HDR, 8.04%), POLB (BER, 6.54%), MUS81 (HDR, 6.42%), NBN (HDR, 6.31%), and EXO1 (MMR, 6.26%), while the most frequently deleted genes were BRCA2 (HDR, 6.44%), XRCC2 (HDR, 6.38%), and CUL5 (NER, 6,28%)." (PMID 36081518, 2022). "However, recent research focused on the mechanisms that XRCC2 involved in the oncogenesis of cancer are not available yet." (PMID 32258128, 2020). "Therefore, XRCC2 may increases LARC radioresistance by repairing DNA double-strand breaks and preventing cancer cell apoptosis." (PMID 26320178, 2015). "However, whether the XRCC2 promoter is hyperactivated in tumors and its potential use as a tool for the transcriptional targeting of cancer diagnosis and therapy has not been characterized." (PMID 29549248, 2018).
tumor (48 papers, 2011 to 2025). "Prior research had revealed correlation of XRCC2 polymorphisms/expression with tumor risk and drug sensitivity." (PMID 39090304, 2024). "Radiation induces an abnormal increase in the expression level of XRCC2 in lung cancer cells, which causes them to resist the damaging effects of radiation on tumour cell DNA." (PMID 37679817, 2023). "The results indicated that γH2AX expression of tumor tissues following olaparib+RT treatment was significantly greater in XRCC2-deficient CRC cells." (PMID 35643812, 2022). "The results of these xenograft tumor model experiments confirmed that olaparib increased the radiosensitivity of XRCC2-deficient CRC cells." (PMID 35643812, 2022). "We also confirmed the effectiveness of this combination treatment in vivo using XRCC2-deficient tumor xenografts, which had delayed growth relative to xenografts with empty vectors." (PMID 35643812, 2022). "Another case study on Polish population (Warsaw) also said that the feasible character of XRCC2 gene polymorphism is responsible for neoplastic diseases." (PMID 32458654, 2020). "The observation of XRCC2 mutations in our patient tumour data expands on these previous animal and cell line studies, further supporting an important role for this pathway." (PMID 25609015, 2015). "Further analysis of one additional treatment-refractory tumour sample revealed some evidence for a second XRCC2 mutation." (PMID 25609015, 2015). "The associations between XRCC2 expression in pretreatment biopsy tissue samples and postoperative histological tumor regression and long-term prognosis were evaluated in 67 LARC patients who received PRT." (PMID 26320178, 2015). "Furthermore, our mouse xenograft experiments indicated that RT + olaparib had greater anti-tumor effects and led to long-term remission in mice with XRCC2-deficient tumors." (PMID 35643812, 2022). "Interestingly, two of four BRCA1 mutated cases presented a response to platinum retreatment while in two patients with XRCC2 mutation, one presented a stable disease and the other tumor progression." (PMID 31060523, 2019). "In glioblastoma, inhibition of XRCC2 expression increases the radiosensitivity of tumour cells to radiation." (PMID 37679817, 2023). "Tunicamycin (Tm)-activated sXBP1 bound to the TGTCAT element and suppressed XRCC2 expression to prevent tumor proliferation in vivo." (PMID 36204047, 2022). "In patients with LUSC, XRCC2 expression was correlated with tumor stage (P < 0.05), with the highest gene expression being observed in stage II." (PMID 34486486, 2021). "Another Chinese case control study says that in CRC tissue, the expression of XRCC2 is inflated and notable interdependences are also found among positive XRCC2 expression, tumor size, Dukes’ stage and TNM stage." (PMID 32458654, 2020). "In both cases the VAFs were lower than in case 1 suggesting either a sub clonal XRCC2 wild type population within the tumors or admixtures of non tumor cells in the sorted samples." (PMID 30870501, 2019). "In summary, our results strongly indicate that virus-mediated delivery of constructs built upon the XRCC2 promoter holds great potential for tumor diagnosis and therapy." (PMID 29549248, 2018). "We found that shRNA-mediated XRCC2 suppression rendered T84 tumor cells more sensitive to radiation treatment as evaluated by the colony formation assay." (PMID 24481064, 2014).
tumor (continued). "A recent study showed that the incidence of spontaneous breast and intestinal tumorigenesis was higher in XRCC2+/+ mice than in XRCC2+/− animals, implicating a possible role for XRCC2 in affecting tumor cells’ radiosensitivity." (PMID 24481064, 2014). "The results suggested that the knockdown of XRCC2 enabled XRCC2 tumor cells to escape from G1 phase and to arrest in the G2/M phase." (PMID 24481064, 2014). "Other tumor-activatable promoters could also be studied that have less leakiness such as XRCC2 or hTERT in the future." (PMID 35327423, 2022). "The X-ray repair complementing defective repair in Chinese hamster cells 2 (XRCC2) gene plays an important role in the homologous recombination repair (HRR) pathway at the same time can be said a functional member for taking part in tumor progression." (PMID 32458654, 2020). "We identified both known and novel somatic copy number aberrations (12p, MDM2, and RHBDD1) and mutations (XRCC2, PIK3CA, RITA1) including candidate markers for platinum resistance that were present in a primary tumor of mixed histology and that remained after tandem autologous stem cell transplant." (PMID 30870501, 2019). "Besides, we also observed that MSH4, NBN, NEIL2, OGG1 and XRCC2 were downregulated in both HPV-positive tumor cell lines when compared to the HPV-negative one." (PMID 30674977, 2019). "Given that inhibiting of XRCC2 expression can enhance radiosensitivity of tumor cells, strategies to knockdown XRCC2 expression may improve the efficacy of radiation therapy in clinical settings." (PMID 24481064, 2014). "In addition, tumor xenograft studies suggested that XRCC2 silencing inhibited tumorigenicity after radiation treatment in vivo." (PMID 24481064, 2014). "Therefore, XRCC2 abnormal expression can lead to genomic instability and promote tumor development and progression." (PMID 24481064, 2014). "Similarly, the molecular mechanisms by which XRCC2 mediates tumor cells’ radiosensitivity remains a subject of future investigation." (PMID 24481064, 2014). "Although several reports have suggested an association between XRCC2 expression and radiosensitivity, it is unclear whether suppression of XRCC2 expression in any tumor cells uniformly facilitates tumor radiotherapy." (PMID 24481064, 2014). "The pathological examination revealed detailed effect of XRCC2 knockdown on tumor growth in vivo." (PMID 24481064, 2014). "Overexpression of XRCC2 appeared in tumor cell lines compared with HEK293." (PMID 24481064, 2014). "As cells arrested in the G2/M phase are generally more sensitive to radiation than those in other phases, it is plausible that the XRCC2-mediated change of the cell cycle may consequently affect the sensitivity of tumor cells to radiation therapy." (PMID 24481064, 2014). "Selected CRC target genes involved in apoptosis (BAX), tumor growth (TGFβRII), WNT pathway (AXIN2, TCF4, WISP3), DNA repair (ATM, ATR, BLM, BRCA1, BRCA2, DNAPKcs, MBD4, MRE11, MSH3, MSH6, RAD50, XRCC2) and PI3-kinase signaling (PTEN) were analyzed for mutations in MSI-positive HGG samples." (PMID 21637783, 2011). "Allele XRCC3-241Met (OR 0.85, 95%CI 0.72–0.99, p < 0.045), XRCC2-41657 T (OR 1.67, 95% CI 1.42–1.96, p < .0001), BRCA1-356R (OR 1.61; % CI 1.37–1.90, p < .0001) and RAD51–135C (OR 5.16; 95% CI 4.29–6.20, p < .0001) strongly correlated with the neoplastic disease." (PMID 30712190, 2019). "Furthermore, a functional relationship between XRCC2 overexpression and reduced radiosensitivity was observed in vivo, and this was consistent with the observations that XRCC2-negative tumor cells exhibited an increase in G2/M cell cycle phase arrest and apoptosis-related cell death." (PMID 26320178, 2015). "Thus, we propose that the inhibiting of XRCC2 expression of tumor cells may enhance their radiosensitivity." (PMID 24481064, 2014). "RAD51 paralogs, including RAD51B, RAD51C, RAD51D, XRCC2 and XRCC3, have emerged as essential tumour suppressors, forming two subcomplexes, BCDX2 and CX3." (PMID 39268578, 2024).
tumor (continued). "The expression of XRCC2 and PARP1 in biopsy tumor specimens collected from 167 LARC patients before treatment with neoCRT followed by surgery indicated that 57 samples (34.1%) were XRCC2+ and 52 samples (31.1%) were PARP1+." (PMID 35643812, 2022). "Five HR cofactors – the RAD51 paralogs RAD51B, RAD51C, RAD51D, XRCC2 and XRCC3 – recently emerged as crucial tumor suppressors." (PMID 32669601, 2020). "Previous studies have shown that miR-7 functions as a tumor suppresser in CRC by targeting oncogenic YY1 and XRCC2." (PMID 27126129, 2016). "Consequently, it has been hypothesized that XRCC2 may enhance tumor radioresistance." (PMID 26320178, 2015). "Therefore, we propose that XRCC2 overexpression may be predictive of tumor resistance to PRT." (PMID 26320178, 2015). "The artificial amiR efficiently inhibited the expression of XRCC2 and XRCC4 genes, sensitizing human tumor cells to radiation-induced death." (PMID 24616890, 2014). "Increased levels of phosphorylated Chk2 were detected in the XRCC2 knockdown cells of the present study compared to the controls cells after IR, and these results suggest that in XRCC2-negative LARC patients, activation of Chk2-dependent signaling may improve tumor cell radiosensitivity." (PMID 26320178, 2015).
renal disease (1 paper, 2023). "Among these genes, Adora2b, Trpc5, Ar, Xrcc2, and Atp1b1 are involved in renal disease and blood pressure regulation." (PMID 37125041, 2023).
XRCC2 also shares sentences with these, for which no sentence is quoted: breast (3 papers); brain cancer (2); brain tumor (2); medulloblastoma (2); oral cancer (2); pharyngeal cancer (2); acute myeloid leukemia (1); adenocarcinoma of the pancreas (1); adenoma (1); autosomal recessive disease (1); bone marrow failure (1); Cenani-Lenz syndrome (1); colon adenocarcinoma (1); dermatitis (1); endometrial tumors (1); esophageal adenocarcinoma (1); esophageal cancer (1); female reproductive diseases (1); fibrosarcoma (1); gastric cardia adenocarcinoma (1); genetic disorder (1); hepatocellular carcinoma (1); laryngeal carcinoma (1); leukemia (1); lymphedema (1); Lynch syndrome (1); meningioma (1); metastatic melanoma (1); mucositis (1); myelomeningocele (1).
A further 12 diseases each share a sentence with XRCC2 in 1 paper.